HMGB1 (high mobility group box 1)
Diseases named in the same sentence as HMGB1 in open-access papers (continued):
Sharing a sentence is not in itself a finding about the gene and the disease.
diabetes (continued). "Consequently, akin to clinical research, only individuals with a more severe form of early diabetes exhibit elevated GFR, as observed in the HMGB1 Flox TMX STZ mice, which are likely compensating to excrete excess glucose." (PMID 38187339, 2024). "It should be noted that since the serum levels of HMGB1 are increased in diabetic individuals, TLR4 activation by this DAMP might also play a role in impaired skin wound healing in diabetes." (PMID 36982926, 2023). "HMGB1 also regulates HSPB1 to maintain mitochondrial morphology and control mitochondrial autophagy, which plays an important role in myocardial remodeling after diabetes." (PMID 37065747, 2023). "RAGE is a receptor for other specific ligands, including HMGB1 (high mobility group box 1 protein; recognized as a DAMP protein), whose expression increases in hyperglycemic conditions or in conditions such as obesity, systemic inflammation or diabetes." (PMID 34395368, 2021). "Resveratrol may confer protection against the diabetes-induced breakdown of BRB through SIRT1 upregulation and HMGB1 downregulation." (PMID 32722545, 2020). "Moreover, treatment with the SIRT1 activator resveratrol attenuates the diabetes-induced downregulation of SIRT1, accompanied by reduced expression of HMGB1 and RAGEs." (PMID 32722545, 2020). "Noteworthily in the present study, Cs-A did dramatically extenuate but not extinguish the adverse effect of diabetes or HMGB-1 on the rat retina." (PMID 32019593, 2020). "While HMGB1 interactions with TLRs may also be important, the HMGB1-RAGE interaction plays a more important part in the context of diabetes and periodontal diseases." (PMID 31929852, 2019). "Although numerous published studies have focused on the role of RAGE and its ligands in diabetes, little is known about the expression of AGE, HMGB1 and RAGE in diabetic submandibular glands (SMGs), as well as the effects of diabetes on apoptosis and proliferation markers in that tissue." (PMID 28099448, 2017). "Two clinical studies showed significantly higher serum HMGB-1 level in coronary artery disease patients with diabetes than in patients without diabetes." (PMID 27847406, 2016). "It is demonstrated that subjects with diabetes exhibited higher serum HMGB-1 levels compared with nondiabetic patients." (PMID 27847406, 2016). "In addition, diabetes induced upregulation of RAGE, ERK, and NF-κB; however, oral administration of glycyrrhizin, a specific inhibitor of HMGB-1, attenuated NF-κB activation." (PMID 27847406, 2016). "Our current data that plasma HMGB1 levels wereassociated with diabetes independent of BMI further confirmed this phenomenon." (PMID 26317615, 2015). "Constant glycyrrhizin intake from the onset of diabetes did not affect the metabolic status of the diabetic rats, but it significantly attenuated diabetes-induced upregulation of HMGB1 protein and mRNA, activated ERK1/2, cleaved caspase-3, and glutamate." (PMID 24733965, 2014). "HMGB1 could bind to RAGE, which belongs to the immunoglobulin superfamily, a kind of transmembrane protein, playing an important role in diseases such as diabetes and inflammatory diseases." (PMID 24837834, 2014). "HMGB1 plays a critical role in hyperglycaemia-induced cardiomyocyte apoptosis via ERK-dependent activation of Ets-1, thus leading to myocardial dysfunction in diabetes." (PMID 25210949, 2014). "In our laboratory, we recently demonstrated that diabetes induced significant upregulation of retinal expression of HMGB1, RAGE, activated NF-κB, activated ERK1/2, and ICAM-1 and that intravitreal administration of HMGB1 in normal rats mimics the effect of diabetes." (PMID 24733965, 2014). "On the day of admission to ICU, plasma sRAGE, HMGB-1 and thrombomodulin levels are significantly higher in all critically ill patients with or without diabetes as compared with healthy control subjects." (PMID 21871056, 2011).
diabetes (continued). "Similar findings were observed in the validation set: serum HMGB1 levels were also higher in patients with DKD compared with patients with long-term diabetes but without CKD nephropathy or in healthy control people without diabetes." (PMID 38481996, 2024). "The binding of RAGE to other ligands (e.g., high mobility group box 1, S100 proteins, lipopolysaccharides, and amyloid-β) can result in pathological processes via the activation of intracellular RAGE signaling pathways, including inflammation, diabetes, aging, cancer growth, and metastasis." (PMID 35216202, 2022). "HMGB-1 is a nuclear protein involved in inflammation, angiogenesis and tissue regeneration and it has been shown that it is overexpressed in diabetic patients compared to patients without diabetes." (PMID 36244983, 2022). "It is possible that the trafficking of HMGB1, and other lung-derived DAMPs may be responsible for heightened extra-pulmonary inflammation that manifest in COPD patients presenting with ventricular dysfunction, myocardial infarction, diabetes or hypertension." (PMID 32855420, 2020). "In addition, Zhao and coworkers showed that calmodulin-dependent protein kinase IV (CaMKIV), a protein kinase involved in neuropathic pain, and HMGB1 were upregulated in DRG of rats treated with streptozotocin (STZ), used to induce diabetes and neuropathic pain." (PMID 31835864, 2019). "In addition, elevated HMGB1 plasma levels are related to other chronic inflammatory conditions in non-HIV-infected individuals including diabetes mellitus and cancer." (PMID 29992171, 2018). "HMGB1 levels were not correlated to presence of malignancy, heart disease or diabetes." (PMID 30194360, 2018). "Interestingly, treatment with LPLI decreases the diabetes-induced transcription of HMGB1 and RAGE, with reductions of AGE, RAGE, HMGB1 and TNF-α protein expression, possibly down-regulating NF-κB in diabetic SMGs, indicating that LPLI has a potent anti-inflammatory effect." (PMID 28099448, 2017). "Wang and coworkers reported that genetic inhibition of HMGB-1 improved myocardial function in diabetic cardiomyopathy, suggesting that HMGB-1 contributes to myocardial dysfunction in diabetes and inhibition of HMGB-1 might have therapeutic potential in treatment of diabetic cardiomyopathy." (PMID 27847406, 2016). "However, inhibition of TLR2 or TLR4 in diabetes exhibited reduced inflammatory responses, indicating that TLR2 or TLR4 might mediate HMGB-1-induced inflammation in DN." (PMID 27847406, 2016). "Since we did not observe an alteration in the expression of HMGB1 and HSP70, which are damage-associated molecular patterns (DAMPs) that activate TLR4, in the adrenal glands of diabetic rats and mice, we evaluated if diabetes changes the gut bacterial composition in Swiss-Webster mice." (PMID 40496562, 2025). "We did not observe differences in the relative amount of HMGB1, S100B, S100A6 and SOD1 proteins in SN harvested from diabetic and control mice at six months after diabetes induction in our experiment (P ≥ 0.05)." (PMID 37462767, 2023). "Compared to the control group, the AAA groupexhibited significantly higher levels of current smoking history, hypertension,HMGB1, HMGB2, TnI, NT-pro BNP, and D-Dimer (p < 0.05), while showinglower levels of never smoked, statin use, diabetes, sTREM-1, eGFR, TG, TC, andHbA1c (p < 0.05)." (PMID 40776964, 2025). "We observed an inverted J-shaped nonlinear relationship between serum HMGB1 levels and eGFR (p-nonlinear=0.007, p<0.001, knots=6, AIC=2137.97), after excluding the confounding factors of age, sex, hypertension, smokers, and duration of diabetes." (PMID 38481996, 2024). "In addition, we previously observed that levels of HMGB-1 were higher in patients with PAD and diabetes mellitus compared to those without diabetes mellitus." (PMID 36244983, 2022).
hepatocellular carcinoma (154 papers, 2010 to 2026). A malignant tumor that arises from hepatocytes. "While blockade of HMGB1 reduced the accumulation of tumor-associated M2 macrophages and inhibited the growth of hepatocellular carcinoma in mice." (PMID 36059534, 2022). "Mainly, HMGB1-RAGE signaling has a significant functional role in the development as well as progression of hepatocellular carcinoma; for instance, the expression of HMGB1 is higher in HCC conditions and associated with clinicopathological characteristics." (PMID 35829833, 2022). "By Ki67 immuno-fluorescence staining assay, the expression levels of Ki67 in shLuc tumors were much higher than shHMGB1 tumors, indicating that loss of HMGB1 reduces hepatoma proliferation in vivo." (PMID 32788720, 2020). "Blockage of ROS and HMGB1 is able to reduce accumulation of tumor-associated M2 macrophages and attenuate the hepatoma growth in mice." (PMID 32788720, 2020). "This indicates that hepatoma-derived HMGB1 promotes tumor-associated M2 macrophage accumulation and tumor growth in hepatoma-bearing mice." (PMID 32788720, 2020). "Upregulation of MMPs with HMGB1 has been associated with cancer cell proliferation of colon, pancreatic, pulmonary, hepatocarcinoma, and hepatocellular carcinoma cell lines." (PMID 32443845, 2020). "A number of studies have indicated that HMGB1 overexpression is associated with a worse prognosis in patients with several inflammation-associated cancers, such as hepatocellular carcinoma, colorectal cancer, and cervical carcinoma." (PMID 30891101, 2019). "In summary, we identified two risk-associated polymorphisms (rs1045411 and rs2070600) and more importantly a joint impact of seven polymorphisms from the HMGB1/RAGE axis in susceptibility to hepatocellular carcinoma." (PMID 28187002, 2017). "DNA methylation of CpG islands in target gene promoters can alter gene expression; for instance, methylation of miR-129-2 has been linked to the regulation of high mobility group box 1 expression in human hepatocellular carcinoma." (PMID 29156793, 2017). "First, it is interesting to notice a leading role played by rs1045411 and rs2070600 polymorphisms that conferred a significant increased risk for hepatocellular carcinoma, and the two polymorphisms were respectively resided in HMGB1 and RAGE genes." (PMID 28187002, 2017). "Furthermore, in hepatocellular carcinoma models, Osthole-mediated apoptosis appeared linked to HMGB1-related inflammatory signaling, highlighting its potential to modulate the local immune niche." (PMID 42193122, 2026). "However, HMGB1 has also been shown to promote hepatocellular carcinoma and associate with radiation resistance of bladder cancer cells." (PMID 34568076, 2021). "Previous studies have reported the HMGB1 polymorphisms might efficiently predict the risk of susceptibility to different cancers such as hepatocellular carcinoma, uterine cervical neoplasia as well as colorectal cancer." (PMID 29617336, 2018). "Haplotype analysis showed that the T-C-T haplotype (rs1045411-rs2249825-rs1415125) in HMGB1 gene was associated with a 2.47-fold (95% CI: 1.41-4.34; P = 0.002) increased risk of hepatocellular carcinoma compared with the commonest C-C-T haplotype after adjustment." (PMID 28187002, 2017). "As a member of damage-associated molecular patterns (DAMPs), extracellular high-mobility group box 1 (HMGB1) plays a critical role in hepatocellular carcinoma (HCC) progression." (PMID 33661757, 2021). "Hepatocellular carcinoma (HCC)-secreted exosomes contain high mobility group box 1 (HMGB1), which is responsible for the promotion of T-cell immunoglobulin and mucin domain 1 (TIM-1)+ Breg cells." (PMID 40443670, 2025). "HMGB1 is critical in the progression of liver injuries and related diseases, being implicated in several conditions, including NAFLD, hepatocellular carcinoma, and HIRI." (PMID 40422225, 2025).
hepatocellular carcinoma (continued). "Previous studies have shown that under hypoxic conditions in hepatocellular carcinoma, HMGB1 can be passively released and induce caspase-1 activation through activation of TLR4 and RAGE signaling pathways, thus promoting cancer cell invasion and metastasis." (PMID 40969278, 2025). "For instance, exosomal HMGB1 derived from hepatocellular carcinoma cells has been shown to encourage the expansion of TIM-1+ regulatory B cells via the HMGB1-TLR2/4-MAPK signaling pathway." (PMID 37670933, 2023). "HMGB1 levels increased significantly in the culture medium of human and mouse colorectal cancer and hepatoma cell lines treated with hypoxia for 24 hours." (PMID 36942262, 2023). "HMGB1 promotes human hepatocellular carcinoma invasiveness and metastases by facilitating the epithelial-to-mesenchymal transition and promoting an immune suppressive TME." (PMID 36831371, 2023). "A recent study showed that HMGB1 derived from hepatocellular carcinoma triggers M2 macrophage polarization through TLR2 and autophagy." (PMID 36982351, 2023). "During hypoxia, HMGB1 up-regulates mitochondrial biogenesis in human hepatocellular carcinoma, promoting tumor survival and proliferation." (PMID 37110415, 2023). "Studies in hepatocellular carcinoma showed that TLR2 was involved in the immune escape initiated by HMGB1 and induced the senescence and autophagy of hepatocytes." (PMID 37153547, 2023). "The hypoxic environment generated in the center of the hepatocellular carcinoma (HCC) causes the release of damage-associated molecular pattern (DAMP) proteins, including High Mobility Group Box 1 (HMGB1) and mitochondrial DNA (mtDNA)." (PMID 36942262, 2023). "Very recently HMGB1 released from dead tumor cells was proved to be a trigger of repopulation of the residual hepatocellular carcinoma cells after radiotherapy." (PMID 37880798, 2023). "This is consistent with previous reports which showed that HMGB1 induced upregulation of miR-21 in hepatocellular carcinoma." (PMID 35586052, 2022). "This is consistent with the finding that HMGB1 induced miR- 21 expression in hepatocellular carcinoma." (PMID 35586052, 2022). "More recently, using a murine model of hepatocellular carcinoma, HMGB1 released from necrotic hepatocytes was found to bind TREM-1 using immunoblotting and SPR, with a binding KD of 35.4 x 10-6 M." (PMID 35784361, 2022). "For example, the HCV patients with hepatocellular carcinoma (HCC) shows significantly higher levels of serum HMGB1 relative to that of healthy controls (92.1 ± 50.6 ng/mL vs. 7.0 ± 5.9 ng/mL)." (PMID 34008469, 2021). "In hepatocellular carcinoma (HCC), RAGE overexpression and interaction with HMGB1 induce tumor-associated macrophage activation and NF-κB expression to promote tumoral proliferation, invasion, and metastasis." (PMID 33568752, 2021). "This activity associated with higher levels of HMGB1 in hepatoma cells and was curbed by pharmacological blockage of the receptor for advanced glycation end product (RAGE)/HMGB1 axis or the mitogen‐activated protein kinases ERK1/2 pathway." (PMID 32697038, 2020). "Blockage of ROS and HMGB1 reduces accumulation of M2 macrophages within the hepatoma and attenuates hepatoma growth in mice." (PMID 32788720, 2020). "Taking these results together, we have demonstrated that hepatoma-derived HMGB1 facilitates M2 macrophage recruitment and tumor growth while blockage of HMGB1 and ROS inhibits hepatoma growth in mice." (PMID 32788720, 2020). "Here, we uncovered a new regulatory mechanism of the HMGB1-triggered TLR2/NOX2/autophagy axis in hepatoma-prompted M2 macrophage polarization." (PMID 32788720, 2020).
hepatocellular carcinoma (continued). "Remarkably, Hepa1‐6 hepatoma cells were also found to express far higher levels of HMGB1 as compared to RAW264.7 macrophages." (PMID 32697038, 2020). "In this study we show that hepatoma-derived HMGB1 stimulates ROS via the TLR2/NOX2 axis to trigger autophagy-regulated M2 macrophage polarization." (PMID 32788720, 2020). "Increased plasma or serum levels of HMGB1 have been found in various types of tumors, such as colon carcinoma, chronic lymphocytic leukemia and hepatocellular carcinoma, and promotes tumor progression." (PMID 32938467, 2020). "Then we used a murine in situ hepatoma model, which was set up by intrasplenic injection of 106 shLuc- or shHMGB1-ML-14a cells to mice, to examine the extrinsic role of HMGB1 on hepatoma growth." (PMID 32788720, 2020). "Hepatoma-derived HMGB1 stimulates NOX2-dependent ROS generation via TLR2 to trigger autophagy formation, which leads to lysosomal degradation of NF-κB p65 and hence maintains the M2 macrophage polarization." (PMID 32788720, 2020). "We then went further to examine the regulatory role of hepatoma-derived HMGB1 in hepatoma-bearing mouse." (PMID 32788720, 2020). "lncRNA TP73-As1 modulated cell proliferation through miR-200a dependent HMGB1/RAGE regulation in hepatocellular carcinoma." (PMID 30069164, 2018). "Here, we provide the first evidence that HMGB1 also interacts with the critical viral protein HBx and that this binding facilitates autophagy in hepatocytes and hepatoma cells." (PMID 29316268, 2018). "Previous studies have demonstrated the elevation of serum HMGB1 levels in patients with gastric or cervical cancers and hepatocellular carcinoma." (PMID 30245980, 2018). "The results of another study conducted by Cheng suggested the level of HMGB1 in serum as a useful marker for the evaluation of tumor stage in hepatocellular carcinoma." (PMID 30245980, 2018). "HMGB1 in the cytosolic fraction of HepG2 hepatocellular carcinoma cells was also bound to the metformin beads, and their association was competitively inhibited by metformin in a concentration-dependent manner." (PMID 28373282, 2017). "Bearing this in mind, we selected seven well-characterized polymorphisms from HMGB1 and RAGE genes to assess their genetic susceptibility to hepatocellular carcinoma in a large Han Chinese population." (PMID 28187002, 2017). "High levels of HMGB1 have been correlated with worsened disease outcome in most types of cancers, including colorectal cancer, bladder cancer, and hepatocellular carcinoma." (PMID 28536706, 2017). "Studies have shown that HMGB1 is over-expressed in many kinds of cancer tissues, including breast, lung, colon, nasopharyngeal, prostate, hepatocellular carcinoma, and melanoma." (PMID 26499944, 2016). "Meanwhile, higher HMGB1 expression was detected in late stage patients with hepatocellular carcinoma and squamous-cell carcinoma of the head and neck." (PMID 27391431, 2016). "Increased HMGB1 is observed in many cancer types, including prostate cancers, leukemia, colorectal and hepatocellular cancer and is related to occurrence, progression, and metastasis." (PMID 25652880, 2015). "In hepatocellular cancer, HMGB1 binds to mitochondrial DNA released from hypoxic cells and promote tumor cell growth by TLR-9 activation." (PMID 26854151, 2015). "HepG2 cells (human hepatocellular carcinoma cell line) can be induced to release HMGB1 by treatment with LPS or TNF-α in a time- and dose-dependent fashion." (PMID 25187820, 2014). "The release of HMGB1 post IFN-γ/Con A treatment by lysosomal cell death will provide a link to further anti-hepatoma CD8+ cytotoxic T cell activation." (PMID 22163006, 2011). "Ferroptotic HMGB1 also promotes immunosuppressive remodeling by recruiting myeloid-derived suppressor cells (MDSCs) and upregulating PD-L1 expression, fostering immune escape in hepatocellular carcinoma." (PMID 41465435, 2025).